IGFBP5 (insulin like growth factor binding protein 5)
Diseases named in the same sentence as IGFBP5 in open-access papers (continued):
Sharing a sentence is not in itself a finding about the gene and the disease.
breast cancer (continued). "There are many findings and assumptions about the role of IGFBP5 and it is very crucial to identify the role of IGFBP5 in cancer progression, especially in breast cancer." (PMID 26569312, 2015). "This NLS is believed to mediate the translocation of IGFBP-5 to the nuclear compartment as IGFBP-5 was detected in the nucleus of the breast cancer cell line T47D, lung fibroblasts from patients with IPF, vascular smooth muscle cells and osteosarcoma cells." (PMID 26103640, 2015). "It seems therefore that, by downregulating IGFBP5, MSCs and CAFs coordinately induce a wide range of changes in breast cancer cells." (PMID 26515727, 2015). "Our microarray data also proved that IGFBP5 was one of the upregulated genes in all the breast cancer samples compared with their adjacent normal tissues (p = 0.0004, median difference = 1.379)." (PMID 26569312, 2015). "Wild-type IGFBP5 translocated to the nucleus where it exerted inhibitory effects on proliferation and migration of MDA-MB-435 cells suggesting that IGFBP-5 cellular compartmentalization dictates its role in breast cancer cell metastasis." (PMID 26103640, 2015). "IGFBP-5 expression was also shown to be correlated with increased survival rate and to help maintaining tumor sensitivity to tamoxifen in breast cancer patients." (PMID 26569312, 2015). "IGFBP5 induces apoptosis in mammary epithelial cells, breast cancer cells and osteosarcoma cells but prevents apoptosis in neuroblastoma cells, C2 myoblasts and human stellate cells." (PMID 25230843, 2014). "Insulin like growth factor binding protein 5 (Igfbp5) plays multiple roles in breast cancer progression and is a prognostic factor." (PMID 21589862, 2011). "In contrast, an anti-apoptotic role of IGFBP5 has been reported, for instance, in myogenesis, in breast cancer cells grown in vitro, and in gingival epithelial cells." (PMID 20163708, 2010). "The matter becomes complicated when attempting to understand the function of IGFBP5 in cell culture assays in vitro, studies have shown that IGFBP5 induces breast cancer cell apoptosis." (PMID 19341485, 2009). "Results from gain-of-function studies conducted via forced expression of IGFBP5 in breast cancer cell lines has shown a surprising inhibitory effect of IGFBP5 on cell proliferation." (PMID 19341485, 2009). "Recently, Jurgeit and colleagues also analyzed cytoplasmic trafficking and cellular localization of IGFBP5 in T47D breast cancer cell line and in paraffin sections of involuting mammary glands." (PMID 19341485, 2009). "In breast cancer, IGFBP-5 interacts with various extracellular matrix components, and it is regulated by proteolysis and hormones that act on the mammary gland." (PMID 19476635, 2009). "In contrast, immunohistochemistry studies of breast cancer tissues have shown IGFBP5 to be localized mainly to the cytoplasm." (PMID 19341485, 2009). "Deletion of the last 5 amino acids of NLS in IGFBP5 eliminated nuclear localization of IGFBP5 and significantly promotes breast cancer cell proliferation and motility." (PMID 19341485, 2009). "This study provides supporting evidence that cellular localization of IGFBP5 is important for its functions in breast cancer." (PMID 19341485, 2009). "Next, we transfected each expression construct into MDA-MB-435 breast cancer cells to establish stable clones overexpressing either wild-type or mutant IGFBP5." (PMID 19341485, 2009). "We transfected both wild-type and mutant IGFBP5 expression vectors into the MDA-MB-435 breast cancer cells, and established several stable cell lines overexpressing these vectors." (PMID 19341485, 2009). "A closer look at the eight Ox-E/ER genes linked to these growth factors revealed that most (EGR1, PHLDA1, IGFBP5, TAGLN, DAB2, and FHL2) have been associated with breast cancer." (PMID 18631401, 2008).
breast cancer (continued). "IGFBPs are upregulated in malignant breast epithelial cells with evidence in vivo that IGFBP-5 is overexpressed in the cytoplasm of breast cancers and their lymph node metastases on tissue microassay immunohistochemistry (IHC)[B6]." (PMID 15642160, 2005). "Notably, nuclear IGFBP5 has been shown to reduce cell proliferation and migration in breast cancer cells, whereas cytoplasmic IGFBP5 increases cell growth and migration." (PMID 38351010, 2024). "Moreover, our results indicate potential regulation of DSC1 by NF-κB inhibitor parthenolide as we identified parthenolide to reduce DSC1 protein levels in MCF7 breast cancer cells as well as expression of IGFBP5, LACRT genes and proliferative pathway." (PMID 37620794, 2023). "IGFBP5 is considered to be a positive indicator for the prognosis of breast cancer." (PMID 37088808, 2023). "IGFBP5 was revealed to stimulate cell migration in breast cancer." (PMID 37620794, 2023). "This inconsistency in suggestions of IGFBP5 role in breast cancer could be due to IGFBP5 protein cellular localization that seems to affect its ability to promote or inhibit breast cancer progression." (PMID 37620794, 2023). "In this review, the focus lies on the biological effects and regulation of IGFBP5 in breast cancer." (PMID 36093095, 2022). "In breast cancer, estrogen is a critical regulator of IGFBP5 transcription." (PMID 36093095, 2022). "While some trends are more visually apparent, such as the enrichment within glioma and breast cancer cell lines for high-IGFBP5 expressing cell lines, expression within other types of cancer such as bone is more nuanced and contains both high- and low-expressing cell lines." (PMID 36465383, 2022). "It is interesting to note that Igfbp5 is upregulated during involution and it has been hypothesized that Igfbp5 may act as a tumor suppressor in breast cancer, indicating that mammary gland position may have an influence on timing of involution." (PMID 34437559, 2021). "Furthermore, bladder cancer, colorectal cancer, and breast cancer tissues also contain high levels of IGFBP5, but few studies have explored the expression and mechanism for IGFBP5 in human GC." (PMID 32801999, 2020). "Thus despite the small difference in the risk estimates between never and current EPT, replication of this G x E interaction reinforced what we found previously, implicating the role of the IGFBP5 gene and estrogen pathway in breast cancer." (PMID 31605532, 2020). "Moreover, cytoplasmic accumulation of IGFBP-5 in breast cancer cells interacted with sphingosine kinase and protein kinase C, stimulating antiapoptotic effects." (PMID 29515523, 2018). "Palpable mammary tumors were observed in female transgenic mice starting at 4 months of age, with an average of 8.4 months, and were confirmed to have low expression of IGFBP‐5 and increased phosphorylated Akt." (PMID 26951623, 2016). "IGFBP5 accumulates in the cytoplasm and is related with bad prognoses in the breast cancer tissue." (PMID 26569312, 2015). "We concluded that the discovery of coordinately expressed genes related with IGFBP5 might contribute to understanding of the molecular mechanism of the function of IGFBP5 in breast cancer." (PMID 26569312, 2015). "Collectively, the tissue level of IGFBP-5 in breast cancer may be both prognostic and predictive biomarker for tamoxifen and IGF inhibitory agents." (PMID 26217584, 2015). "IGFBP5 is an important regulatory protein in breast cancer progression." (PMID 26569312, 2015). "So we anticipate that IGFBP5 could be a possible modifier on metastatic capacity of breast cancer through regulating COL1A1 or MMP11." (PMID 26569312, 2015). "How stromal cells downregulate IGFBP5 expression in breast cancer cells has still to be determined." (PMID 26515727, 2015).
breast cancer (continued). "In conclusion, our results suggest that MSCs and CAFs are able to trigger downregulation of IGFBP5 expression in ERα-positive breast cancer cells, such as MCF-7 cells, and, as a consequence, induce a number of changes in signaling pathway activities and gene expression." (PMID 26515727, 2015). "Similarly, the effects of IGFBP-5 on cellular proliferation and invasion in breast cancer studies appear to be cell line dependent." (PMID 25475528, 2014). "Interestingly, in a previous report, expression of IGFBP2 and IGFBP5 were correlated with increased lymph node metastasis in T1 breast carcinoma." (PMID 23767917, 2013). "In our next investigation, we will determine whether Parc is the key regulator that renders IGFBP5 cytoplasmic in breast cancer cells in tumors and contributes to the growth and migration stimulatory effect." (PMID 19341485, 2009). "However, a major difficulty in understanding how IGFBP5 functions in this capacity is the paradoxical observation that ectopic overexpression of IGFBP5 in breast cancer cell lines results in suppressed cellular proliferation." (PMID 19341485, 2009). "It is conceivable that IGFBP5 in breast cancer tissues binds to another protein that modifies its conformation and deletion of the NLS has a similar effect on the conformation, which may prove to be important for IGFBP5 localization and function." (PMID 19341485, 2009). "There are contradictory findings and implications regarding whether IGFBP5 has enhancing and inhibitory effects on cells in breast cancer." (PMID 19341485, 2009). "IGFBP5 may play a regulatory role in cell growth and invasion in breast cancer." (PMID 38627939, 2024). "In addition, IGFBP5 may be a promoter or suppressor of tumor growth in a variety of cancers, including breast cancer." (PMID 38896333, 2024). "In MDA-MB-435 cells (a kind of breast cancer cell), wild-type IGFBP5 could translocate to the nucleus and inhibit cell proliferation and migration; on the contrary, NLS-mutant was mainly detected in the cytoplasm and enhanced the proliferation and migration of cells." (PMID 36865533, 2023). "However, since IGFBP5 is localized primarily to the cytosol in patient tissues, it remains unclear whether nuclear localization of IGFBP5 contributes to breast cancer progression." (PMID 36465383, 2022). "Interestingly, several other HDAC1/7-SE upregulated targets, such as SNPH, CCANG4, PREX1, IGFBP5, IL34 and BCAS4 also demonstrate remarkable level of breast cancer associated over-expression, providing additional support for the relevance of the ET-125 signature." (PMID 36038558, 2022). "In addition, IGFBP5 acts as an oncogene in different cancers such as gastric cancer, colorectal cancer, prostate cancer, glioblastoma, human melanoma, and breast cancer." (PMID 34362467, 2021). "However, the role of IGFBP-5 in breast cancer has largely escaped attention." (PMID 31046834, 2019). "Although IGFBP5 has been associated with various types of cancers, acting in oncogenic or tumor-suppressive roles, such as breast cancer, osteosarcoma, head and neck squamous cell carcinoma, neuroblastoma, or prostate cancer, little is known about the role of IGFBP5 in human MM." (PMID 26010068, 2015). "Hence, evaluation of IGFBP2, IGFBP5 along with β-catenin may provide a stronger predictive value for the prognosis of breast cancer." (PMID 23767917, 2013). "Serum samples from 154 dogs with mammary tumors (31 benign, 123 malignant) and 39 healthy controls were analyzed using a custom multiplex immunoassay detecting autoantibodies against AGR2, HAPLN1, IGFBP5, and TYMS, normalized to anti-BSA levels." (PMID 41562247, 2026). "In domains 4 and 13, 2 differentially expressed genes, IGFBP5 and CRISP3, have dense linkages with the treatment of mammary carcinoma." (PMID 39804726, 2025). "IGFBP5 regulates IGF-IR expression, migration and MMP-9 secretion induced by IGF-I and/or insulin, and the spheroids formation in MCF-7 breast cancer cells." (PMID 38896333, 2024).
breast cancer (continued). "We demonstrate a novel function of IGFBP5 in the regulation of IGF-IR expression, migration and MMP-9 secretion induced by IGF-I and/or insulin, and in the spheroids formation in MCF-7 breast cancer cells." (PMID 38896333, 2024). "Osteopontin-a upregulates the levels of glucose in breast cancer cells through STAT3, likely via its transcriptional targets apolipoprotein D and IGFBP5." (PMID 38039408, 2023). "For some known genes related to breast cancer (e.g., MYC, IGFBP5, CCND1, ESR1), we confirmed epithelial cells showed higher expression levels." (PMID 37340002, 2023). "Whereas IGFBP5 reduces effectiveness of PI3K inhibitors, IGFBP5 enhances the effectiveness of tamoxifen in ER+ breast cancers." (PMID 36465383, 2022). "Wnt signaling, like the cases previously discussed regarding breast cancer and NASH/NAFLD, provides another instance in which IGFBP5 appears to have a highly context dependent mechanism which is in some cases pro-tumorigenic." (PMID 36465383, 2022). "Collectively, the analysis of the effect of expression of PAPP‐A both in vitro and in vivo suggests that PAPP‐A is a pregnancy‐dependent oncogene that promotes the formation of mammary tumors characterized by a TACS‐3 signature and low IGFBP‐5 levels." (PMID 26951623, 2016). "Further functional and protein-protein interactions studies are needed to clarify a likely correlation between IGFBP5, COL1A1 and MMP11 considering the metastasis process in breast cancer." (PMID 26569312, 2015). "Another drastically down-regulated gene, IGFBP5, induces cell adhesion and increases cell survival in MCF-7 human breast cancer cells." (PMID 24260584, 2013). "The present study showed that deletion of 5 amino acids (214 to 218, RGRKR) within the NLS of IGFBP5 resulted in change in subcellular location of IGFBP5 and increased proliferation and motility of MDA-MB-435 breast cancer cells." (PMID 19341485, 2009). "IHC of tissue microassays confirms a tumour-specific upregulation of IGFBP-5 and IGFBP-2 in primary breast cancers and their lymph node metastases." (PMID 15642160, 2005). "Breast cancer cells typically express several IGFBPs, with IGFBP-2, IGFBP-3, IGFBP-4 and IGFBP-5 being observed most often." (PMID 15642160, 2005). "Moreover, overexpression of IGFBP5 in MDA-MB-435 breast cancer cells promotes a lower cell growth rate and motility than wild type MDA-MB-435 cells and the localization of IGFBP5 in the nucleus." (PMID 38896333, 2024). "Findings demonstrate that IGFBP5 does not induce migration in MCF-7 breast cancer cells, but it induces migration in TNBC MDA-MB-231 cells." (PMID 38896333, 2024). "IGFBP5 is a key member of the insulin-like growth factor (IGF) axis which plays an important role in cellular differentiation, proliferation and apoptosis in breast cancer." (PMID 31605532, 2020). "The positive correlation of DDR1 with IGF-IR and IGFBP2, but not with AKT, INSR or IGFBP5, was further confirmed in the TCGA breast cancer dataset." (PMID 26655502, 2016). "On the other hand, the failure of T47D cells to react this way upon exposure to stromal cells indicates that breast cancer cells do not necessarily respond to stromal cells by inducing changes in IGFBP5 and Bcl-3 expression." (PMID 26515727, 2015). "Others have also shown that a high IGFBP-5/4 ratio predicted sensitivity to an IR/IGF-IR TKI in a pre-clinical breast cancer model and was correlated with a worse breast cancer outcome, suggesting that this ratio may be indicative of patient response." (PMID 26029167, 2015). "IGFBP5 protein expression has been reported to be a marker of poor outcome independent of the ER and PR status in patients with breast cancer." (PMID 23483937, 2013). "IGFBP5 and IGFBP2 are overexpressed in breast cancer tissues, and are involved in apoptosis." (PMID 19843326, 2009).
breast cancer (continued). "If Parc turns out not to be the regulator, identification of a new IGFBP5 regulator in the cells will certainly opens a new window into the pathogenesis of breast cancer biology." (PMID 19341485, 2009). "A recent study also revealed that IGFBP4 mRNA expression is an independent prognostic factor in breast cancer, and that patients with ER-positive breast cancer with higher levels of IGFBP4 tumor mRNA expression and lower levels of IGFBP5 mRNA had a better prognosis." (PMID 18928543, 2008). "The noncanonical activities of IGFBP5 promote cellular attachment to ECM proteins, a phenotype associated with invasion and metastasis, and ectopic expression of IGFBP5 results in decreased invasion of melanoma and breast cancer cells." (PMID 36465383, 2022). "Meanwhile, MiR-1207-5p can target STAT6 to promote breast cancer growth, DNMT1 is a critical factor responsible for DNA methylation modification, VEGFA can trigger aberrant angiogenesis and induce immune evasion, and IGFBP5 is capable of regulating the insulin-like pathway." (PMID 34760687, 2021). "Furthermore, a high mRNA ratio of IGFBP-5/IGFBP-4 from patients’ tissue enhanced the power of its poor prognostic value, and also predicted resistance to the IGF-1R and INSR TKI, BMS-536924, in a breast cancer cell line." (PMID 26217584, 2015). "Since some changes as induced by IGFBP5 downregulation could be mimicked by insulin, some by CoCl2 and others neither by insulin nor CoCl2, it is likely that IGFBP5 fulfills several different functions in breast cancer cells." (PMID 26515727, 2015). "Our data also show that, even within the subgroup of ERα-positive breast cancer, cancer cells may or may not respond to MSCs and CAFs by downregulating IGFBP5 expression indicating that ERα-positive breast cancers are a heterogeneous group also in respect to their interactions with stromal cells." (PMID 26515727, 2015). "We demonstrate that IGFBP5 is a repressor of IGF-IR expression, but is not a repressor of IR expression in MCF-7 breast cancer cells." (PMID 38896333, 2024). "IGFBP5 is a repressor of IGF-IR expression, but it is not a repressor of IR in MCF-7 breast cancer cells." (PMID 38896333, 2024). "In basal breast cancer cells, activation of WNT/β-catenin signalling by WNT3A represses IGFBP5; however, the mechanism has not been identified." (PMID 35048158, 2022). "However, the role of IGFBP5 in cellular processes that mediate tumor growth and metastasis through the IGF/IGFR system in breast cancer has not been studied in detail." (PMID 38896333, 2024).